FOXP3 (forkhead box P3)
Diseases named in the same sentence as FOXP3 in open-access papers (continued):
Sharing a sentence is not in itself a finding about the gene and the disease.
tumor (continued). "Secondly, different kinds of FOXP3 isoforms may function differently in tumor metastasis." (PMID 36235242, 2022). "In addition, surgery wounding also significantly supported an increase in neutrophils and regulatory T cells in the primary tumor, indicated by increased expression of lymphocyte antigen 6 complex locus G6D (Ly6G, p < 0.05) and forkhead box P3 (Foxp3, p < 0.05), respectively." (PMID 36325601, 2022). "Moreover, the miR192‐5p antagomir repressed the FOXP3 mRNA expression in tumour tissues." (PMID 35969010, 2022). "In addition, immunosuppressive regulatory T cells (Foxp3+ CD4+) increase with time in both models, but only E0771 tumors display an early growth period when a majority of tumor-associated CD4+ T cells are immunostimulatory, resulting in a more favorable environment for CPA responses." (PMID 36187936, 2022). "Similarly, Radix glycyrrhizae polysaccharides have been shown to downregulate the number of Treg cells in the microenvironment of H22 tumor xenograft mice by decreasing the expression of Foxp3 in Treg cells while upregulating the Th1/Th2 ratio in serum; as a result, inhibiting tumor growth." (PMID 36500466, 2022). "However, FOXP3-positive Tregs with immune inhibitory functions also accumulated at the tumor sites." (PMID 35763240, 2022). "Seeing that there were TIL cultures with a greater proportion of CD4+FOXP3+ T-cells, it is unclear whether the in vitro expansion environment induced FOXP3 expression or there were already greater proportions of CD4+FOXP3+ T-cells within the tumour specimens prior to expansion." (PMID 35158816, 2022). "However, the effects of FOXP3 on tumor metastasis and its interaction with traditional Chinese medicine (TCM) remain unclear." (PMID 36235242, 2022). "Similarly, the CD8+ to FOXP3+ ratio in the MMR-d tumor was also elevated." (PMID 35547873, 2022). "Interestingly, AIL-treated tumor supernatant exhibited more significant inhibitory effects on Treg differentiation and Foxp3 mRNA levels, suggesting that the inhibitory effect of AIL on Treg differentiation is mainly determined by molecules in the tumor supernatant." (PMID 36522774, 2022). "In addition, considering our multivariate analysis suggesting a role for CD4+/FoxP3+ cells with PD-L1 expression, we postulate that this interaction might potentially play a central role towards tumor progression." (PMID 36268020, 2022). "FOXP3-expressing regulatory T (Treg) cells might suppress anti-tumor immune response." (PMID 34898543, 2021). "Additionally, ursolic acid carried by liposomes could also effectively reduce tumor CD4+ CD25+ Foxp3+ T cells and MDSCs in 4T1 breast tumor-bearing mice." (PMID 33572626, 2021). "The tumor-infiltrating RORC-Tregs we have shown to be linked to poor patient outcomes and associated with tumor androgenesis were selected based on elevated levels of FOXP3, CTLA4, GITR, RORC and GATA3 transcripts in the whole tumor, not from individual T-cells." (PMID 34681642, 2021). "Our results showed that the increased Foxp3+ Treg cells, along with the scanty CD8+ T cells, were associated with MitoX-induced autophagy-dependent PAI-1 secretion, suggesting that tumor autophagy modulates the tumor immune microenvironment in response to chemotherapy via the secretory pathway." (PMID 33809137, 2021). "However, recent studies have found that high densities of intra-tumoral Foxp3(+) T cells in an earlier CRC stage showed a positive correlation with overall survival, and distinct subpopulations of tumor-infiltrating Foxp3(+) T cells contribute in opposing ways to the determination of CRC prognosis." (PMID 33919941, 2021). "Also, previous work suggests the role of FOXP3 in tumour immunity in cancer patients." (PMID 34541823, 2021). "Our IHC staining found that RANKL might be derived from tumor-infiltrating CD25+FOXP3+ Treg cells." (PMID 33795653, 2021).
tumor (continued). "However, in the tumor margins, we found that the presence of high infiltrations of CD3+, CD8+, or FoxP3+ T lymphocytes were associated with TNM stages I-II (p = 0.021, p = 0.022, and p = 0.012, respectively) and absence of lymph node metastases (p = 0.010, p = 0.003, and p = 0.004, respectively)." (PMID 34440038, 2021). "Importantly, CD8+Foxp3+ Treg cells display cytotoxic activity which can suppress tumor during GVHD." (PMID 34262560, 2021). "Moreover, CD4+ CD25+ FOXP3 regulatory T cells (TREG) is one of the most studied cell population in the study of tumor microenvironment, which displayed the immunosuppressive role and could be a target of immunotherapy in the HCC." (PMID 34527684, 2021). "Interestingly however, while not statistically significant, our analysis revealed that high infiltrations of CD3+, CD8+, or FoxP3+ T lymphocytes in the tumor margins resulted in increased overall survival of 13.4 (p = 0.117), 7 (p = 0.224), and 14 months (p = 0.092), respectively." (PMID 34440038, 2021). "In addition to tumor cell expression of FoxP3, there are other markers that may also influence the prognostic utility of Tregs." (PMID 34141625, 2021). "However, the concomitant use of the vaccine and tadalafil resulted in a decrease in PD-L1+ macrophages at the tumor edges, an intra-tumoral decrease in FoxP3+ T-regs, and an increase in intra-tumoral CD8+ CTLs associated with an augmentation of the CD69 early activation marker." (PMID 34885150, 2021). "To investigate whether the loss of ability to promote a mesenchymal phenotype indeed came from knockdown of the LFPRLR in Tregs themselves, we isolated tumor Tregs from untreated Foxp3+EGFP Balb/c mice and ex vivo treated with 1 μM Control SMO or LFPRLR SMO for 48 h." (PMID 34375938, 2021). "We recently reported that in CD4+CD25+Foxp3+ T-regulatory (Treg) cells, Mef2d is required for the acquisition of an effector Treg (eTreg) phenotype and for the activation of an epigenetic program that suppresses the anti-tumor immune responses of conventional T and B cells." (PMID 34290714, 2021). "While FoxP3 can be transiently expressed by recently activated T cells in humans, the expression of this transcription factor also marks a population of regulatory T lymphocytes that can downregulate immune responses and, consequently, dampen anti-tumor immune mechanisms." (PMID 34440038, 2021). "S100A8 expression in tumor cells (TCs) and immune cells (ICs) was assessed by immunohistochemistry, and its association with clinicopathologic features and infiltration of other IC subsets including CD4+, CD8+, and FOXP3+ tumor-infiltrating lymphocytes (TILs) and PD-L1+ ICs was evaluated." (PMID 33146829, 2021). "Our findings show that the intestinal RORγt+ Foxp3+ Treg cell population depends on an intact autophagy machinery, which represent a potential target to enhance Treg cell activity in order to control intestinal inflammation or to restrict Treg cell-mediated tumor tolerance." (PMID 34512629, 2021). "Thus, the potency of CR in dampening tumor growth and metastasis could be explained by the inhibition of FoxP3+CD8+ Tregs, which, in turn, results in increased proliferation of antitumor cytotoxic T cells (CD8+ and CD4+)." (PMID 34707136, 2021). "Indeed, in addition to its clear role of FOXP3 in the immunosuppressive activity of Tregs, its expression in normal non-hematopoietic cells as well as in some cancer cells has been shown to participate in tumor growth control." (PMID 33671179, 2021). "However, the local increase of Foxp3 (+) cells could be used to suppress antitumor immunity in a final phase of tumor formation." (PMID 33919941, 2021). "Our results found that MDSCs (CD11b+Gr1+) and Tregs (CD4+CD25+Foxp3+) were elevated significantly on days 21 and 28 after tumor implantation, indicating that both Tregs and MDSCs might affect host tumor immune response." (PMID 33469123, 2021).
tumor (continued). "According to these results, we speculate that T cells that express IL-32 may have a contradictory role that promotes IFNγ expression in CD8+ T cells, which enhances the antitumor activity, and induces CD4+ T cells Foxp3 expression, which suppresses tumor immune response." (PMID 34414188, 2021). "Noteworthy, the CD8+/FOXP3+ TILs ratios in both tumor nests and stroma were consistently higher in tumors harboring negative expressions of NANOG and SOX2; however, significant associations were only reached between the tumoral CD8+/FOXP3+ ratio and both SOX2 and NANOG." (PMID 34201050, 2021). "In another study of the PROMIX trial, a decrease to low levels (<10%) of FOXP3+ T-lymphocytes in biopsies taken after cycle 2 of NAC was significantly associated with an improved DFS, whereas concentration changes of CD163 macrophages during NAC were unrelated to survival or tumor response." (PMID 34771604, 2021). "Furthermore, the relationship between METTL8 and FOXP3 may be a main role in tumor immune escape for LSCC patients." (PMID 33816462, 2021). "Therefore, the inhibition of these interactions might lead to the impairment of specific functions of FOXP3 and Treg activity and thus be beneficial in the development of vaccines and tumor therapies." (PMID 33671179, 2021). "The development of FOXP3 inhibitors for cancer treatment should be able to impair the immunoregulatory functions of FOXP3 on T-cells without altering the anti-proliferative activity that FOXP3 might play in tumor cells." (PMID 33671179, 2021). "Interestingly, we found that tumor-infiltrating CD25+FOXP3+Treg cells were the major producers of RANKL within the microenvironment of RANK-expressing CRC, which may provide a reference for the treatment of CRC metastasis." (PMID 33795653, 2021). "This indicated that even if Foxp3+ cells may potentially dampen lymphocyte function, they do not completely abolish the associated anti-tumor activities in immunologically “hot” areas with CD8+ T cell nfiltration." (PMID 33803245, 2021). "In addition, the stromal CD20+/FOXP3+ ratio was significantly associated with tumor recurrence, being lower in non-recurrent cases." (PMID 33494389, 2021). "In other words, USP22 may inhibit the immune response to tumor cells by directly acting on FOXP3." (PMID 34179009, 2021). "Indeed, although CD8+ cytotoxic T immune infiltrate was observed, Foxp3+ immunosuppressive regulatory T cells were also recruited in tumor areas displaying high cyto-nuclear ZO-1 that may potentially result in an overall immunosuppressive environment." (PMID 34938731, 2021). "The anti-tumor potential of hIL-15-ABD was associated with tumor microenvironment (TME) regulation, including the activation of NK cells and CD8+ T cells, the reduction of immunosuppressive cells (MDSCs and Tregs) and the suppression of immunosuppressive factors (IDO, FOXP3 and VEGF)." (PMID 33918641, 2021). "Some important immune-associated genes, such as granzyme B, IFN-γ, IL-2, IL-12, FoxP3 and STING, are regulated via epigenetic mechanisms in immune or/and cancer cells, as are immune checkpoint molecules (PD-1, CTLA-4, TIM-3, LAG-3, TIGIT) expressed by immune cells and tumor-associated stromal cells." (PMID 34930302, 2021). "However, it implies that the FOXP3+ T cells that were detected in NSCLC tumor sections may either represent bona fide Treg cells or recently activated effector Th cells (Th1, Th2, Th17 or Tfh)." (PMID 34868011, 2021). "Thus, VISTA may function as a protective factor by increasing FoxP3+ T cell infiltrates in the tumor microenvironment." (PMID 34465822, 2021). "Interestingly, among the top genes upregulated in the TdTOSX+ CD45+ subsets versus the CD45 single positive populations, we found many genes expressed by tumor promoting immune cells, such as regulatory T cells (i.e. Foxp3) and gamma-delta T cells (i.e. Tcrg-C1)." (PMID 32755539, 2020).
tumor (continued). "There is an argument that FOXP3+ TILs may have heterogeneous properties that are affected by the tumor site, and possibly the molecular subtype, mirroring different contexts within different tumor microenvironments." (PMID 32498695, 2020). "Given that CD4+ T cells isolated from tumor tissue were enriched for Tregs, we hypothesized that the ratio of Tregs to Th in tumors would correlate with the capacity of the resultant DCs to induce FoxP3+ Tregs." (PMID 32973804, 2020). "Furthermore, there was an increase in the Tregs subset (CD3+CD45+CD4+CD25+Foxp3+) in the cisplatin (∗∗∗P < 0.001 vs. T), moxibustion (∗∗P < 0.01 vs. T), and combinatorial therapy (∗∗P < 0.01 vs. T) groups compared with that in the untreated tumor-bearing mice." (PMID 33456484, 2020). "IDO1 levels were associated with aggressive clinico-pathologic features of the tumor such as extrathyroidal extension and multifocality, suggesting that disruption of antitumor immunity by IDO1 expression, and thus, infiltration of FoxP3+ Treg cells may contribute to tumor progression in PTMC." (PMID 33986723, 2020). "Furthermore, we detected the presence of T-bet+ Tregs (CD3+ CD4+ T-bet+ Foxp3+) only at tumor site." (PMID 32182707, 2020). "Tumor-infiltrating lymphocytes, such as GrB+ natural killer cells or effector T cells, are regarded as a positive prognostic marker in a clinical setting, while FoxP3+ regulatory T cells represent immune suppression, and are associated with an unfavorable outcome in a wide range of tumors." (PMID 32121641, 2020). "In addition, the prognostic values of FOXP3+ T cells in the tumor were also controversial." (PMID 32377339, 2020). "Besides, it was also reported that the smaller the tumor diameter the higher expression of Foxp3." (PMID 32626535, 2020). "However, it appears that FOXP3 rather FOXP3Δ3 functions as a tumor suppressor in HCC." (PMID 33116119, 2020). "Interestingly, the sensitivity of the various lymphocyte populations to ionizing radiation in vivo was variable: the tumor infiltrating FOXP3+ Treg cells were more resistant compared with CD8+ T cells, and may dominate the tumor milieu after radiotherapy." (PMID 32974178, 2020). "Moreover, CD60+INOS− TAMs that infiltrated tumors of CRC patients have been associated with increased CD8+Foxp3+ Treg cells in the tumor stroma, being a negative prognostic factor in patients with CRC." (PMID 32674255, 2020). "Moreover, IL‐6 induced CD4+Foxp3+ Treg migration into tumor sites by upregulating CXCR1 expression." (PMID 32931642, 2020). "However, there were lower FOXP3+ regulatory T-cells in metastatic sites than the primary tumor." (PMID 32199452, 2020). "Furthermore, PGE2 promotes recruitment of T regs to the tumor site and induces Foxp3 in T cells." (PMID 31811337, 2020). "Moreover, Bregs might disable the cellular immune response against the tumor by promoting the conversion of CD4+/CD25− T lymphocytes to FoxP3+ Tregs, thereby, enabling tumor growth and the development of metastasis." (PMID 32602047, 2020). "The significance of the demonstration that nivolumab causes an increase in the proportion of CD4+ cells that expressed Foxp3 within the peripheral blood compartment remains unclear since most of the existing literature has focused on CD4+FoxP3+ population within the tumor infiltrating lymphocytes." (PMID 32183719, 2020). "Interestingly, one study has shown that anlotinib could enhance the ratio of CD8/FoxP3+ T cell in tumor tissues thus altering the tumor microenvironment." (PMID 33680942, 2020). "One of such immune subsets is the tumor-associated macrophages (TAMs) which are polarized into M2 macrophage phenotype by IL-10, TGF-β, IL-4, or IL-13 present in the TME, and drive tumor progression by supporting angiogenesis and recruitment of CD4+FoxP3+ T regulatory cells (Tregs)." (PMID 33117354, 2020). "Consequently, mice with Foxp3-conditional knockout of HIF-2α are resistant to tumor growth." (PMID 33024109, 2020).
tumor (continued). "Recent studies suggest that tumor-specific sympathetic denervation inhibits tumor progression, contributes to tumor-induced changes in metabolism, and reduces the expression of immune checkpoint molecules, such as programmed death-1 (PD-1), programmed death ligand-1 (PD-L1), and FOXP3." (PMID 33117814, 2020). "For the first time we showed that high bacterial load in the tumor combined with increased iNOS expression is a favorable prognostic factor (HR = 0.1824; p = 0.0123), while high bacterial load combined with the increased number of FOXP3+ cells is a marker of poor prognosis (HR = 4.651; p = 0.0116)." (PMID 32933105, 2020). "Regarding other immunosuppressive molecule expression, a retrospective study on surgically resected TETs revealed a high expression of IDO and Foxp3 in 13% and 16% of Tms, respectively, and both associated with high grade tumor histology, but had no survival differences." (PMID 33260538, 2020). "Thus, inducing upregulation of OX40 in intratumoural pDCs as well as Foxp3+ Tregs in combination with other anti-cancer treatments may enhance anti-tumour immune responses and clinical benefit." (PMID 32645977, 2020). "The FOXP3/miR-146/NF-kB axis limits tumour growth and could be a valuable target for therapy." (PMID 32188472, 2020). "Indeed a large meta-analysis on the prognostic value of FoxP3 showed that high Treg infiltration is associated with inferior OS in several tumor types, but not in HNSCC." (PMID 32602047, 2020). "However, numerous studies have found negative correlations between FoxP3 T regulatory cells and survival including one study of 115 cases of NMIBC which found an inverse correlation between FoxP3 cell frequency within the tumor (as % of CD3+ve cells) and recurrence-free survival." (PMID 31824850, 2019). "In addition, correlations between CD20+ and CD4+FOXP3+ were seen, implying their potential functional associations within the TME that may negatively impact the infiltration of immune cells into tumor areas." (PMID 31166985, 2019). "However, the role of FOXP3 as a tumor suppressor has also been documented." (PMID 30782783, 2019). "In addition, UXT also interacts with many other well-known tumor-associated transcription factors, such as NF-κB, EVI1, GATA4, FOG2, NKX2.5, and Foxp3, which suggests that UXT may regulate tumorigenesis though multiple signaling pathways." (PMID 31481081, 2019). "Alternatively, a conventional naïve CD4+ T cell may encounter a tumor-associated (‘self’) or tumor-specific (‘neo’) antigen in the tumor environment, become activated, and under the influence of an immunosuppressive tumor microenvironment, differentiate into an induced FOXP3+ (‘iTreg’)." (PMID 31635338, 2019). "Hence, it has been difficult to precisely discern the role of pTreg cells in Treg‐mediated tumour immunosuppression, although comparison of tumour growth and immune infiltrates in wild‐type and Foxp3 CNS1 knockout mice should allow the functional contribution of pTreg cells to be defined." (PMID 31032905, 2019). "Additionally, responders to ipilimumab had a reduction in the percentage of FoxP3+ cells within the tumor post-treatment with ipilimumab indicating that CD16-expressing monocytes may contribute to intratumoral Treg depletion in vivo." (PMID 31892360, 2019). "Indeed, the balance of effector T-cells represented by CD8+ TILs and Treg cells in tumors determines the functional outcome of immune responses, such that the CD8+/FOXP3+ Treg TILs ratio has been shown to be a better predictor of prognosis and tumor outcome in many tumors." (PMID 31640798, 2019). "On the contrary, GATA3+ T helper 2 (Th2) cells and FOXP3+ regulatory T lymphocytes (Tregs) downregulate antitumor immune response by impairing antigen presentation, activity, and cytotoxicity of other immune cells, thus promoting tumor growth and immune tolerance." (PMID 31016433, 2019).